STK24 (serine/threonine kinase 24)
Description:
Serine/threonine-protein kinase that acts on both serine and threonine residues and promotes apoptosis in response to stress stimuli and caspase activation. Mediates oxidative-stress-induced cell death by modulating phosphorylation of JNK1-JNK2 (MAPK8 and MAPK9), p38 (MAPK11, MAPK12, MAPK13 and MAPK14) during oxidative stress. Plays a role in a staurosporine-induced caspase-independent apoptotic pathway by regulating the nuclear translocation of AIFM1 and ENDOG and the DNase activity associated with ENDOG. Phosphorylates STK38L on 'Thr-442' and stimulates its kinase activity. In association with STK26 negatively regulates Golgi reorientation in polarized cell migration upon RHO activation. Also regulates cellular migration with alteration of PTPN12 activity and PXN phosphorylation: phosphorylates PTPN12 and inhibits its activity and may regulate PXN phosphorylation through PTPN12. May act as a key regulator of axon regeneration in the optic nerve and radial nerve. Part of the striatin-interacting phosphatase and kinase (STRIPAK) complexes. STRIPAK complexes have critical roles in protein (de)phosphorylation and are regulators of multiple signaling pathways including Hippo, MAPK, nuclear receptor and cytoskeleton remodeling. Different types of STRIPAK complexes are involved in a variety of biological processes such as cell growth, differentiation, apoptosis, metabolism and immune regulation.
Synonyms: MST-3; MST3; STK3; MST3B; STE20; HEL-S-95
Tractability: Small molecule: a structure with a bound ligand is known; a high-quality ligand is known; it has a high-quality binding pocket; it belongs to a druggable protein family. PROTAC: ubiquitination databases record sites on it; its protein half-life has been measured; a small molecule that binds it is known.
Target class: STE protein kinase group; STE protein kinase STE20 family; STE protein kinase YSK subfamily; Protein Kinase; Kinase; Enzyme
Chemical probes: JA310 (high quality), MR24 (high quality)
Safety:
Unwanted effects reported when the protein is acted on. In parentheses: how it was acted on, where the effect was seen, and who reports it.
cardiac arrhythmia (cardiovascular system; source: Lamore et al. (2017))
Gene: Protein-coding gene on chromosome 13 (98,445,185 to 98,577,940, reverse strand). Ensembl gene ENSG00000102572.
Subcellular location: Cytoplasm; Nucleus; Membrane
Subcellular location (Human Protein Atlas): Cytosol; Nucleoli
Pathways (Reactome):
Programmed Cell Death: Apoptotic cleavage of cellular proteins; Apoptotic execution phase
Gene Ontology:
Molecular function: cadherin binding; protein binding; protein serine/threonine kinase activity; protein kinase activity; ATP binding; protein serine kinase activity
Biological process: cellular response to oxidative stress; cellular response to starvation; execution phase of apoptosis; intrinsic apoptotic signaling pathway in response to oxidative stress; negative regulation of cell migration; protein autophosphorylation; protein phosphorylation; regulation of axon regeneration; intracellular signal transduction; signal transduction
Cellular component: cytoplasm; cytosol; extracellular exosome; FAR/SIN/STRIPAK complex; nucleolus; nucleus; Golgi apparatus; nucleoplasm; membrane
Genetic constraint (gnomAD): Loss-of-function variants: 17 observed, 47.92 expected, observed/expected ratio (o/e) 0.35, 90% interval 0.24 to 0.53. The upper end of that interval is the gene's LOEUF score, 0.53, which puts it in group 2 of 6, group 1 being the genes least tolerant of losing a copy. Missense variants: 366 observed, 521.18 expected, observed/expected ratio (o/e) 0.7, 90% interval 0.64 to 0.77. Synonymous variants: 192 observed, 211.67 expected, observed/expected ratio (o/e) 0.91, 90% interval 0.81 to 1.02.
Homologues: Orthologues: chimpanzee STK24 (98% identical), macaque STK24 (97% identical), pig STK24 (96% identical), mouse Stk24 (95% identical), rabbit STK24 (95% identical), dog STK24 (95% identical), rat LOC134486345 (94% identical), guinea pig STK24 (93% identical), tropical clawed frog stk24 (85% identical), zebrafish stk24b (81% identical), zebrafish stk24a (72% identical), Drosophila melanogaster GckIII (62% identical). Paralogues in human: STK25 (72% identical), STK26 (70% identical), MAP4K4 (41% identical), TNIK (40% identical), MINK1 (39% identical), TAOK1 (39% identical), STK10 (37% identical), MAP4K3 (37% identical), STK3 (37% identical), TAOK2 (36% identical), TAOK3 (36% identical), SLK (36% identical), and 23 more.
Diseases named in the same sentence as STK24 in open-access papers:
STK24 is named in the same sentence as 64 diseases in open-access papers, as found by Europe PMC text mining. Sharing a sentence is not in itself a finding about the gene and the disease. The quoted sentences say what the papers report.
breast carcinoma (15 papers, 2013 to 2025). "High levels of STK24 have been associated with a shorter overall survival time among non-small cell lung and breast cancer patients." (PMID 40725809, 2025). "The expression of STK24 is negatively correlated with the overall survival in patients with breast cancer." (PMID 36720310, 2023). "Although STK24 has been identified as an oncogene in breast cancer, it suppresses colon cancer growth." (PMID 37181807, 2023). "High expression of STK24 is correlated with more aggressive breast cancer subtypes and poor prognosis." (PMID 36720310, 2023). "STK24 also contributes to breast cancer development by regulating VAV2/Rac1 signaling cascade." (PMID 37181807, 2023). "STK24/MST3 is overexpressed in breast cancers and promotes proliferation and tumorigenicity." (PMID 30514397, 2018). "Depletion of PDCD10, STK24, and MST4 in breast cancer cells promotes the generation of the p-ERM arc in lamellipodia." (PMID 34156031, 2021). "Previous studies have demonstrated Stk24 positively regulates the cell cycle, cell growth, migration and synapse development in a kinase activity-dependent manner in HEK293, COS-7, breast cancer cells (MDA-MB-231cells and A431 cells), or neurons." (PMID 29760709, 2018). "Interestingly, ANP32A and STK24 were observed to be significantly up-regulated with PRG treatment in nPR(+) T47D cells (panel A1), preliminarily classifying these genes as PRG-inducible biomarkers in Luminal-A breast cancer cells." (PMID 35971177, 2022).
gastric cancer (6 papers, 2020 to 2025). A primary or metastatic malignant neoplasm involving the stomach. "However, the expression of STK24 has been shown to be lower in gastric cancer as compared with matched normal tissues whereas loss of STK24 was found to promote tumorigenicity and distant metastasis in gastric cancer." (PMID 36720310, 2023). "The abundance and character of MDSCs and the level of STK24 protein expression may cause clinicopathological features, especially in more aggressive gastric cancer cases." (PMID 31892988, 2020). "It has been previously reported that STK24 promotes the expansion of myeloid-derived suppressor cells in gastric cancer." (PMID 37181807, 2023). "While STK24 plays an oncogenic role in gastric cancer growth, it can serve as a tumor suppressor in colorectal cancer." (PMID 37181807, 2023). "The current study explores the role of STK24 in tumorigenesis and the immune response of an orthotopic animal model of gastric cancer." (PMID 31892988, 2020). "In the current study, the silencing of STK24 expression in gastric cancer cells increased the infiltration of CD11b+Ly6C+ MDSCs and promoted tumorigenesis in orthotopic gastric cancer." (PMID 31892988, 2020). "The data for STK24 transcript expression were extracted from the Oncomine database for gastric cancer, and the focus was on normal vs. cancer patient datasets." (PMID 31892988, 2020). "We propose a novel strategy for the treatment of gastric cancer by enhancing the levels of the STK24 protein; the increased levels of STK24 will reduce the number of MDSCs and will therefore reduce their activity." (PMID 31892988, 2020). "The knockdown of the STK24 gene increased the tumor growth in an orthotopic model of gastric cancer." (PMID 31892988, 2020). "An analysis of the relative expression of the STK24 protein in the normal tissues and gastric cancer tissues indicated that the STK24/β-actin ratio in the normal samples was significantly greater than the ratio in the gastric cancer samples (P<0.0001)." (PMID 31892988, 2020). "To determine the clinical significance of STK24 in human gastric cancer, we analyzed the expression of the STK24 gene in the Kaplan‐Meier Plotter and Oncomine databases." (PMID 31892988, 2020). "In the current study, analyses with the Kaplan-Meier Plotter and Oncomine databases revealed that the downregulation of STK24 is a predictor for a poor prognosis for gastric cancer patients." (PMID 31892988, 2020). "In the current study, we detected that STK24 inhibits the expansion of CD11b+Ly6C+ cells and F4/80+ macrophages and inhibits the tumorigenicity of gastric cancer." (PMID 31892988, 2020). "To study STK24-mediated immunity in gastric cancer, we investigated the splenocyte subtypes in an orthotopic animal model of gastric cancer." (PMID 31892988, 2020). "Our results further indicate that STK24 is important for immune regulation during the tumorigenesis of gastric cancer." (PMID 31892988, 2020). "In the present study, it was demonstrated that STK24 was upregulated in NSCLC tissues as compared with normal lung tissues, and NSCLC cells with higher expression of STK24 had stronger proliferation, migration, and invasion potential, which was on contrary to the function of STK24 in gastric cancer." (PMID 36720310, 2023). "Therefore, previous studies have implied that STK24 plays an important role in immune regulation, but the regulatory mechanisms of gastric cancer are incompletely understood." (PMID 31892988, 2020). "In the current study, we suggest that STK24 plays an immunoregulatory role in gastric cancer." (PMID 31892988, 2020). "The expression of STK24 alters cytokine/ chemokine secretion in gastric cancer cells." (PMID 31892988, 2020). "The immunological effects of STK24 in gastric cancer are less well understood." (PMID 31892988, 2020).
gastric cancer (continued). "To explore whether STK24 plays an important role in gastric cancer development, we further analyzed a published microarray dataset (GSE15459) and identified that these 200 gastric cancer patients had low expression levels of STK24." (PMID 31892988, 2020). "The effects of STK24 in gastric cancer are less well understood." (PMID 31892988, 2020). "In the current study, it is not clear whether the expression levels of the STK24 protein are associated with the MDSCs of tumor biopsies and surgical specimens in patients with gastric cancer." (PMID 31892988, 2020). "The suppression of STK24 increased cell migration by inhibiting CDH1 (E-Cadherin) and enhancing the levels of CD44 in gastric cancer cells." (PMID 37202821, 2023). "We first analyzed the constitutive protein expression of STK24 in human AGS, NCI-N87, MKN45, and mouse M12 gastric cancer cell lines." (PMID 31892988, 2020). "Advanced gastric cancer cases, such as those with a greater number of tumors and a higher occurrence of STK24 expression, had higher MST3 expression levels." (PMID 31892988, 2020).
lung adenocarcinoma (6 papers, 2018 to 2025). A carcinoma that arises from the lung and is characterized by the presence of malignant glandular epithelial cells. "Remarkably, it was found that STK24 was upregulated in both lung adenocarcinoma and lung squamous cell carcinoma." (PMID 36720310, 2023). "We found that STK24 was overexpressed in lung adenocarcinoma (LUAD) tissues." (PMID 37181807, 2023). "However, the significance of STK24 in lung adenocarcinoma (LUAD) remains to be determined." (PMID 37181807, 2023). "To determine the role of STK24 in tumorigenesis, we analyzed STK24 expression in three groups of patient specimen, including colorectal cancer (CRC), lung adenocarcinoma (LUAD), and pancreatic adenocarcinoma (PAAD) by tissue microarray (TMA)‐based immunohistochemistry (IHC)." (PMID 38229183, 2024). "Similarly, Stk24 silencing inhibited the IL-17-induced expression of IL-6, CXCL2, and CCL20 in human lung adenocarcinoma cells A549." (PMID 29760709, 2018).
lung carcinoma (6 papers, 2010 to 2025). "STK24 was recently known to promote tumorigenesis in lung cancer through STAT3/VEGFA signalling pathway." (PMID 40122572, 2025). "KLF5 promotes the proliferation and metastasis of lung cancer cells by promoting the expression of STK24." (PMID 37181807, 2023). "Our findings not only illustrated the important role of STK24 in LUAD but also revealed a possible mechanism that STK24 was upregulated by KLF5 in lung cancer patients." (PMID 37181807, 2023). "Above results promoted us to further illustrate the function of KLF5/STK24 axis in lung cancer cell function." (PMID 37181807, 2023). "Collectively, KLF5 promotes lung cancer cell proliferation and migration and promotes STK24 expression." (PMID 37181807, 2023). "Loss-of-function and gain-of-function experiments demonstrated that STK24 expression in lung cancer cells A549 and H1299 was essential to sustain cell growth and proliferation." (PMID 37181807, 2023). "In this study, we demonstrated that STK24 was overexpressed in lung cancer tissues compared with normal lung tissues, and lung cancer patients with higher STK24 expression levels had shorter overall survival time." (PMID 36720310, 2023). "Nevertheless, the biological function of STK24 in lung cancer progress is still unclear." (PMID 36720310, 2023). "In conclusion, KLF5 upregulation of STK24 promotes lung cancer growth and migration." (PMID 37181807, 2023). "Based on these findings, we proposed that targeting STK24 might be a potential therapy for lung cancer patients with highly expressed KLF5." (PMID 37181807, 2023). "Thus, our findings suggest that STK24 has an oncogenic function for lung cancer cell proliferation and growth." (PMID 37181807, 2023). "Thus, our evidences that STK24 overexpression promoted lung cancer cell proliferation and its knockdown-suppressed cancer cell growth revealed that STK24 acts as an oncogene in lung cancer." (PMID 37181807, 2023). "Interestingly, when KLF5 overexpression promoted lung cancer cell proliferation and migration, the knockdown of STK24 significantly blocked the oncogenic role of KLF5." (PMID 37181807, 2023). "Therefore, KLF5 upregulation of STK24 may contribute to the progression of lung cancer in both cells and patients." (PMID 37181807, 2023). "Furthermore, Krüppel-like factor 5 (KLF5) activated STK24 in lung cancer cells and tissues." (PMID 37181807, 2023). "Thus, STK24 acts as a proliferation inducer for lung cancer." (PMID 37181807, 2023). "Enhanced lung cancer cell growth and migration triggered by KLF5 could be reversed by silencing of STK24." (PMID 37181807, 2023). "Similarly, knockout or knockdown of Stk24 gene failed to alter cultured cell proliferation in human colon cancer cell line HCT116, lung cancer cell line NCI‐H1299, and A549." (PMID 38229183, 2024).
Insulin resistance (5 papers, 2022 to 2025). Increased resistance towards insulin, that is, diminished effectiveness of insulin in reducing blood glucose levels. "STK24 as a member of the mammalian Sre20 kinase family can improve the insulin resistance by inhibiting the insulin signaling pathway, as we all know that insulin resistance is one of the key factors of myocardial fibrosis in DCM." (PMID 35096111, 2022).
colon carcinoma (4 papers, 2022 to 2024). "STK24, which encodes serine/threonine kinase 24, plays a key role in mediating cellular demise in response to oxidative stress in a human colon carcinoma cell line." (PMID 36466095, 2022).
epilepsy (3 papers, 2013 to 2023). A brain disorder characterized by episodes of abnormally increased neuronal discharge resulting in transient episodes of sensory or motor neurological dysfunction, or psychic dysfunction. "Here, we investigated the location and expression pattern of STK24 in epilepsy and observed the change of electrophysiology in the Mg2+‐free‐induced epileptic hippocampal neuronal culture model after overexpressing STK24." (PMID 32436359, 2020). "Moreover, STK24 was identified as a possible binding partner of N-methyl-D-aspartate (NMDA) (glutamate receptor) in a study on epilepsy in mice." (PMID 38328521, 2023). "To examine the role of STK24 on neuronal excitability in epilepsy, we measured miniature excitatory and inhibitory postsynaptic currents (mEPSCs and mIPSCs) of STK24 overexpressed cultured hippocampal neurons and corresponding control neurons in Mg2+‐free medium via whole‐cell recordings." (PMID 32436359, 2020). "According to the fundamental characteristics of STK24, we hypothesize that STK24 may involve in epilepsy." (PMID 32436359, 2020). "In order to figure out whether STK24 has a regulatory effect on epilepsy, the whole‐cell recordings were performed to detect the synaptic transmission of STK24 overexpressed neurons in Mg2+‐free medium, which can simulate spontaneous recurrent epileptiform discharges in epilepsy." (PMID 32436359, 2020). "However, it has not been studied whether STK24 modulates the excitatory synaptic transmission in epilepsy." (PMID 32436359, 2020).
autoimmune disease (2 papers, 2018 to 2019). A disorder resulting from loss of function or tissue destruction of an organ or multiple organs, arising from humoral or cellular immune responses of the individual to their own tissue constituents. "STK24 plays an important role in controlling interleukin 17 (IL-17)-triggered inflammation and autoimmune diseases, since STK24 deficiency or knockdown markedly inhibited IL-17-induced phosphorylation of NF-κB and impaired IL-17-induced chemokines and cytokines expression." (PMID 30804932, 2019). "Collectively, our findings suggest that Stk24 plays an important role in controlling IL-17-triggered inflammation and autoimmune diseases and provides new insight into the therapeutic targets of IL-17-mediated inflammatory disease." (PMID 29760709, 2018).
lung squamous cell carcinoma (2 papers, 2023 to 2024). "Consistently, we observed the enhanced STK24 gene expression in LUAD, lung squamous cell carcinoma (LUSC), and cholangiocarcinoma (CHOL) in HPA data set." (PMID 38229183, 2024).
Anxiety (1 paper, 2023). Intense feelings of nervousness, tension, or panic often arise in response to interpersonal stresses. "There was an association between anxiety levels (HADS-A scores) and genes involved in the activity of excitatory neurotransmitters: PTPRN2 (rs3857647), DLGAP4 (rs8114927), and STK24 (rs9517326)." (PMID 38328521, 2023).
experimental autoimmune encephalomyelitis (1 paper, 2018). An autoimmune demyelinating disease of the central nervous system that is produced experimentally in animals by the injection of homogenized brain or spinal cord in Freund's adjuvant. "In addition, the severity of experimental autoimmune encephalomyelitis was markedly reduced in mice with a deficiency of Stk24 in non-hematopoietic cells." (PMID 29760709, 2018).
keratoconus (1 paper, 2014). A degenerative, structural disorder of the eye, characterized by a cone-shaped protrusion of the cornea. "A recent study in Polish patients with sporadic keratoconus, however, reported that keratoconus-related sequence variants in these genes (DOCK9, IPO5, and STK24) were present only in small number of studied patients indicating that these genes may have minor roles to play." (PMID 25254113, 2014). "Furthermore, this locus contains additional genes, IPO5 (importin 5; OMIM 602008) and STK24 (serine/threonine kinase 24; OMIM 604984), the exact role of which in keratoconus pathogenesis is not known yet." (PMID 25254113, 2014).